INS (insulin)
Diseases named in the same sentence as INS in open-access papers (continued):
Sharing a sentence is not in itself a finding about the gene and the disease.
diabetes (continued). "This highlights the important point that ICI-induced DKA requires ongoing insulin therapy similar to patients with type 1 diabetes mellitus." (PMID 39726058, 2024). "In the fed state, insulin AUC was significantly higher in the AGE supplementation group compared to the diabetes group (p < 0.01), and blood glucose AUC was substantially lower (p < 0.01)." (PMID 38778421, 2024). "In insulin-resistant conditions, such as type 2 diabetes mellitus, GLUT4 expression and/or translocation to the cell plasma membrane is reduced, compromising cell energy metabolism." (PMID 38279251, 2024). "Reviewing the currently available literature on WSS, diabetes mellitus, either the insulin-dependent (type I) or -independent (type II) form with onset in adolescence or early adulthood, was present in 60% of cases including ours." (PMID 39342163, 2024). "Bibliometrics showed that oxidative stress, diabetes, Alzheimer’s disease (AD), cognitive decline, insulin resistance and quercetin were the key words of the symbiotic network." (PMID 39758348, 2024). "Because of the widespread prevalence of diabetes, including a major undersupplied market in Asia, human insulin is in great demand." (PMID 39309966, 2024). "Most participants newly diagnosed with T2D or receiving insulin treatment benefited from either a follow-up call, home visit by a nurse, or diabetes care appointment." (PMID 38632612, 2024). "According to the National Statistics Report of the Centers for Disease Control and Prevention, 5.7% of all U.S. adults (1.7 million adults aged 20 years or older) with diagnosed diabetes use insulin." (PMID 38672255, 2024). "This study will aim to address this problem by bringing together NHS staff, people with diabetes and their family members/carers, to co-design a multimodal intervention to target underpinning factors that can contribute to insulin errors." (PMID 39666732, 2024). "They diligently followed the recommendations of medical professionals, including hormone therapy and insulin treatment for the child’s diabetes, as advised by the endocrinologist." (PMID 39213306, 2024). "In streptozotocin-induced diabetes model, dietary fortification with lycopene mediated increased serum insulin concentrations, decreased urine and blood sugar concentrations, and reduced diabetes-induced pancreatic injury." (PMID 38883868, 2024). "Patients taking drugs to control diabetes include six patients prescribed insulin, eight patients prescribed metformin, and five patients prescribed SGLT2 inhibitor." (PMID 39594155, 2024). "Type 2 diabetes mellitus (T2DM) is one of the most common metabolic disorders resulting from inadequate insulin secretion by pancreatic beta cells or insufficient responsiveness in insulin-sensitive tissues." (PMID 39595124, 2024). "People with DR, regardless of their DKD status, tended to have a longer duration of diabetes, with the use of antidiabetic medication and insulin, higher HbA1c%, and random blood glucose levels." (PMID 38546730, 2024). "In conclusion, FTO plays a critical role in the pathogenesis of diabetes, influencing insulin secretion, insulin sensitivity, and the development of diabetic complications through diverse mechanisms." (PMID 39744011, 2024). "Type 2 diabetes mellitus (T2DM) is a metabolic disorder caused by the combination of insulin resistance and insufficient secretion of insulin compensation." (PMID 39125959, 2024). "Conditions like T1DM or LADA are believed to induce ketoacidosis in patients due to their reduction of insulin needs for the same rationale." (PMID 39598463, 2024). "Afterwards, we applied the same method for feature ranking, and we detected the most relevant factors of the clinical records correlated with past diabetes duration: age, insulin intake, and body-mass index." (PMID 38435625, 2024).
diabetes (continued). "B. fragilis reduced the diabetes incidence from 69% to 33% and the percent of islets with insulitis from 40% to 7%, which doubled the serum insulin level compared with the vehicle‐treated control mice." (PMID 39136533, 2024). "For instance, miR-375 has been used to induce stem cells to differentiate into insulin-producing beta cells, offering potential therapies for diabetes." (PMID 39684593, 2024). "Increased GSK-3 activity has been observed in T2DM patients and mice with diabetes, indicating its involvement in impaired insulin signaling." (PMID 39655056, 2024). "Other clinical entities of diabetes mellitus result from genetic disorders in insulin secretion or activity, anomalies hindering insulin secretion, impairments to the mitochondria, and circumstances compromising glucose tolerance." (PMID 39057600, 2024). "In our study, the borderline p-value of 0.051 regarding the prevalence of diabetes (both oral antidiabetic and insulin-dependent) in the normal weight and obese groups invites a nuanced discussion." (PMID 38398028, 2024). "In diabetes, hyperglycemia initially arises from the failure of cells to fully respond to insulin, a condition referred to as insulin resistance." (PMID 38337727, 2024). "The alarming state of global insulin access in low-resource settings presents a major barrier to diabetes care." (PMID 38939619, 2024). "The prooxidation and proinflammatory effects of UA affect the sensitivity of surrounding tissue cells to insulin, affect glucose homeostasis in the body, and promote the occurrence of diabetes." (PMID 38515506, 2024). "Of particular note, certain DE mRNAs enriched in calcium signaling pathway and type 2 diabetes mellitus pathway play a fundamental in the process of insulin secretion." (PMID 38557554, 2024). "PI3K-Akt signaling is vital for insulin function, and in diabetes, impairments in this pathway can lead to insulin resistance by inducing oxidative stress, protein accumulation and misfolding, mitochondrial dysfunction, inflammation, and apoptosis." (PMID 38326874, 2024). "Diabetes represents a chronic condition characterized by elevated blood glucose levels resulting from insufficient insulin production or impaired insulin action." (PMID 39170342, 2024). "The present report underscores the need for readily available alternatives, such as biosimilar insulins, in the Indian healthcare market to make insulin accessible to every patient with diabetes." (PMID 38910730, 2024). "The primary therapeutic strategies for IR involved using diabetes medications (such as insulin, sulfonylureas, biguanides, and incretins) that stimulated insulin secretion or enhanced insulin sensitivity." (PMID 39737158, 2024). "Clinical evidence further supports the cardiovascular benefits of insulin therapy, particularly in the management of diabetes." (PMID 39125938, 2024). "In our diabetes cohort, only 8 women (2%) received insulin for their diabetes, but overall 89% initiated breastfeeding and 70% of babies were exclusively breastfed during the newborn protocol for hypoglycaemia prevention." (PMID 39627143, 2024). "The purpose of this study was to understand the healthcare provider (HCP) perspective on the extent of suboptimal insulin dosing in people with diabetes (PwD), as well as specific challenges and solutions to insulin management." (PMID 38649812, 2024). "If the correct type of diabetes is diagnosed, then physicians can provide proper management, leading to the discontinuation of insulin treatment with confidence and safety." (PMID 39010018, 2024). "For example, studies show that Japanese individuals with a normal tolerance to glucose have an insulin secretion capacity that is similar to Caucasian patients with diabetes." (PMID 38892604, 2024). "Diabetes is a systemic metabolic disorder characterized by hyperglycemia, arising from either reduced insulin secretion or decreased insulin sensitivity." (PMID 39502877, 2024).
diabetes (continued). "Individuals with diabetes mellitus are unable to produce adequate amounts of insulin, a hormone secreted by the pancreas." (PMID 38378741, 2024). "Promoting the regeneration of islets and improving the production of insulin is essential for the recovery of type 2 diabetes mellitus (T2DM)." (PMID 39062506, 2024). "It has also been established that diabetes is related with decreased AMPK activation as well as impaired insulin signaling." (PMID 38683825, 2024). "Nevertheless, insulin and oral hypoglycemic agents remain the primary pharmaceutical options for managing diabetes mellitus." (PMID 39885962, 2024). "This receptor affects lipid and insulin metabolism and insulin sensitivity and plays a role in disorders such as in dyslipidemia, diabetes, obesity, insulin resistance, and atherosclerosis." (PMID 38791465, 2024). "Studies have shown that postbiotics can improve insulin sensitivity, reduce blood sugar levels, and shorten the course of diabetes." (PMID 39272484, 2024). "Insulin therapy should be initiated when blood sugar is high in patients with newly diagnosed type-2 diabetes mellitus." (PMID 39190215, 2024). "Newly developed underweight group had higher proportion of insulin use, multiple oral hypoglycemic agent administration, and prolonged diabetes mellitus." (PMID 38281993, 2024). "Several medications are available to treat diabetes, such as insulin, insulin sensitizers, and glucose absorption inhibitors." (PMID 38523307, 2024). "Baseline age, BMI, duration of diabetes, HbA1c, eGFR, urinary protein excretion, hemoglobin, plasma albumin, insulin use, RAAS inhibitor use, statin use, and dyslipidemia were comparable in different groups." (PMID 39126619, 2024). "Additional factors such as younger age, long diabetes duration, high HbA1c levels, and insulin treatment were identified as significant contributors to uncontrolled diabetes after a 3-year follow-up." (PMID 38448443, 2024). "With the use of CGM guidance to adjust the insulin regimen, the HbA1c of patients with diabetes and HD decreased from 8.4±1.0% to 7.6±1.0%, and the average glucose value decreased from 9.9±1.9 mmol/L to 8.9±2.1 mmol/L." (PMID 39628691, 2024). "The treatment with AV gel for eight weeks alleviated these deficits related to diabetes, and in some aspects, it was even more effective than insulin." (PMID 38998660, 2024). "Icodec has the potential to simplify the treatment of diabetes that requires insulin therapy, eliminating the discomfort of the daily injection for patients, thus hopefully increasing adherence to treatment." (PMID 38610878, 2024). "For individuals currently taking a non-insulin adjunct (n = 20), BMI was significantly higher compared to those taking insulin only to manage their diabetes (n = 107) (29.4 [25.4, 31.6] kg/m2 vs 24.7 [22.3, 27.2] kg/m2, p = 0.004)." (PMID 38799027, 2024). "The dose of basic insulin in diabetes patients after combined use of GLP-1 RA (WMD −2.74 [−4.26, −1.22], p ≤ 0.001) was significantly reduced." (PMID 39072050, 2024). "Diabetes is a chronic condition brought on by either insufficient insulin production by the pancreas or inefficient insulin use by the body." (PMID 38311623, 2024). "For instance, hypertension was commonly treated with antihypertensive medications such as enalapril and losartan, while diabetes mellitus management included metformin and insulin." (PMID 39597963, 2024). "Multiple studies also demonstrated the beneficial effects of ginger on insulin signaling in the context of diabetes." (PMID 39199328, 2024). "Most patients were started on biologics, some were on methotrexate (dermatology and rheumatology), insulin (diabetes) and isotretinoin (dermatology)." (PMID 38530614, 2024). "We compared kidney outcomes of patients who initiated dapagliflozin or other diabetes medications other than SGLT2i and insulin." (PMID 38328413, 2024).
diabetes (continued). "In some countries, intensive insulin treatment has been suggested for type 2 and other types of diabetes in adults." (PMID 39201842, 2024). "Type 2 diabetes mellitus (T2DM) is a chronic metabolic disorder characterized by a relentless deterioration in insulin sensitivity and a subsequent, progressive decline in pancreatic beta-cell function." (PMID 39072050, 2024). "Our study reinforces the importance of this pathway as a potential target for improving insulin production in diabetes." (PMID 38326874, 2024). "The treatment regimen was mentioned as a complex matter in the care of T1 diabetes, as insulin intake and treatment plans have to be individualized according to the lifestyle and general condition." (PMID 39303284, 2024). "At present, they are being explored for their favorable influence on glycemic indexes and insulin sensitivity making it a favorable choice for managing diabetes." (PMID 39413550, 2024). "Those with higher scores tended to be younger (p < 0.001), have higher BMI (p < 0.001) or require insulin to manage diabetes (p < 0.01)." (PMID 39174748, 2024). "Diabetes is a widespread and complex metabolic disorder characterized primarily by chronic hyperglycemia resulting from impaired insulin secretion, insulin resistance, or both." (PMID 39683932, 2024). "Diabetes is a common metabolic disorder characterized by insufficient insulin production or peripheral insulin resistance." (PMID 39766863, 2024). "diabetes mellitus is a metabolic disease of the endocrine system characterized by elevated blood sugar levels due to disorders in insulin action, and secretion." (PMID 40060282, 2024). "Sources of uncertainty include serious imprecision in the pooled estimates for LDL cholesterol, adverse events, FBG and fasting insulin and insulin sensitivity, and some imprecision for HbA1c, BMI, QoL, and diabetes medication." (PMID 39415400, 2024). "Whilst several national and local interventions/initiatives have been designed to improve insulin safety in UK hospitals, the problem remains, with variable performance in diabetes care across NHS hospitals." (PMID 39666732, 2024). "Diabetes mellitus, commonly known as diabetes, is a medical condition where the body experiences high blood sugar levels due to insufficient insulin production or inadequate insulin response." (PMID 38768222, 2024). "Diabetes is a mixture of metabolic disorders depicted by hyperglycemia resulting from flaws in insulin secretion, insulin action, or both." (PMID 38392186, 2024). "Diabetes is a complex metabolic disorder characterized by high blood glucose levels due to insulin resistance, insufficient insulin secretion, or both." (PMID 38891933, 2024). "Type 2 diabetes mellitus (T2D) is a chronic metabolic disorder prevalent among adults, characterized by insulin resistance and insufficient insulin secretion, resulting in impaired glucose utilization and elevated blood glucose levels." (PMID 39433858, 2024). "As a naturally occurring alkylating antineoplastic agent, STZ is particularly toxic to insulin-producing beta cells in the mammalian pancreas, and can be used alone or in combination with high-fat diet to induce models of diabetes." (PMID 38406276, 2024). "Given the improvement in life expectancy of adults with diabetes, clinicians will soon face the challenge of providing care to more older people with long-duration type 1 diabetes or type 2 diabetes treated with insulin and co-existing long-term conditions." (PMID 39138689, 2024). "Hypertriglyceridemia was seen in 38.1% of the study subjects with poor glycemic control, and it was also found that insulin-treated patients with diabetes mellitus were more likely to have high triglyceride levels." (PMID 39233994, 2024). "Certain medications, like metformin, are known to modulate gut microbiota, thereby influencing insulin sensitivity and aiding in diabetes management." (PMID 38169662, 2024).
diabetes (continued). "Still, in contrast to neonatal diabetes, beta cells are able to process and secrete both the mutant and wild-type insulin." (PMID 39027635, 2024). "The expression of significant proteins of the BBB, such as ZO-1 and occludin, was also evaluated; these results indicated that insulin injections reversed the effects of diabetes and hyperglycemia in the mice and exerted positive effects on the BBB." (PMID 39063010, 2024). "Glucose-responsive hydrogels, another prominent example, undergo swelling or degradation in response to variations in glucose concentration, offering precise insulin delivery for diabetes management." (PMID 39057463, 2024). "This cluster focuses on the biochemistry and metabolism of diabetes, encompassing key terms like apoptosis, ceramide, HDL, insulin, lipidomics, lipotoxicity, palmitate, sphingolipids, and both types of diabetes mellitus." (PMID 39777222, 2024). "The experimental group was characterized by suboptimal metabolic control of 7.1 ± 1%, with a mean diabetes duration of 11.8 ± 6.2 years and an average duration of treatment with a personal insulin pump of 6.9 ± 4.2 years." (PMID 39685536, 2024). "These experiments revealed that, even when mice are at a young age, the islet cell clock influences insulin secretion, glucose levels, and glucose tolerance (i.e., hypoinsulinemic diabetes)." (PMID 39007272, 2024). "This was consistent with an in vivo study that demonstrated that miR-29b plays a role in controlling glucose levels and insulin release by targeting multiple genes, thus impacting the development of diabetes." (PMID 39852135, 2024). "Diabetes, defined by elevated blood glucose levels stemming due to impaired insulin secretion or insulin action, is a significant global health concern." (PMID 39405277, 2024). "Type 2 diabetes mellitus (T2DM) is a metabolic disorder characterized by hyperglycemia resulting from defects in insulin secretion and/or insulin action." (PMID 39075358, 2024). "Reduced insulin secretory capacity and insulin resistance are involved in the pathogenesis of diabetes." (PMID 40607157, 2024). "The etiology of diabetes in humans suggests a multistage model that is primarily based on changes in beta-cell mass and circulating insulin levels." (PMID 39185417, 2024). "The complex pathogenesis of diabetes, that is, the co-existence of insulin resistance and impaired insulin secretion by β-cells, makes the disease progressive." (PMID 39519429, 2024). "Diabetes in seven of these individuals presented before 12 months and was treated with insulin from diagnosis." (PMID 38404237, 2024). "Both the GDM and pre-existing diabetes groups had elevated pre-pregnancy BMI; however, insulin requirements were significantly higher in women with pre-existing diabetes." (PMID 40071056, 2024). "Among enrolled patients, 864 patients (41.5%) had diabetes of whom 32.8% (283 patients) was insulin dependent." (PMID 38310281, 2024). "The gut microbiota can affect the development of diabetes by influencing glucose and lipid metabolism, insulin sensitivity, and inflammation, as well as affecting gut permeability." (PMID 38931292, 2024). "I extend my gratitude to Si-Hoon Kim for his valuable contributions in conducting the induction of diabetes and insulin treatment in the rodent model." (PMID 39070316, 2024). "The focus then shifts to the evolution of insulin delivery systems, showcasing remarkable advancements that have diversified options for individuals with diabetes." (PMID 39065641, 2024). "Both Panax ginseng and Anemarrhena asphodeloides are reported to have anti-diabetic effects, improve insulin sensitivity and attenuate the development of diabetes, hypoglycemic activity, and anti-fatigue effects." (PMID 38693521, 2024). "The microfluidic systems reviewed here for the treatment of diabetes delivered insulin, other peptides, or metformin through transdermal or intraperitoneal injection, oral administration, and inhalation." (PMID 38509342, 2024).